IL2 (interleukin 2)
Diseases named in the same sentence as IL2 in open-access papers (continued):
Sharing a sentence is not in itself a finding about the gene and the disease.
infection (continued). "In late stages of infection, we observed higher amounts of cytokines in lung homogenates from WT mice, as compared to IL-10−/− mice, except for IL-2." (PMID 24205424, 2013). "► When the infected cells were supplemented with IL-2, Prostratin inhibits productive infection with FIV." (PMID 23201205, 2013). "This has also been observed in other infections and suggested to be due to consumption of IL-2 by expanding CD8+ T cells and required for efficient clearance of the invader." (PMID 23696736, 2013). "Vaccine-specific CD4+ T cells producing IL-2 are a desirable outcome of vaccination as these cells are now understood to be preserved in response to infection and to participate in suppression of viremia levels post infection." (PMID 23977084, 2013). "One month after confirmed CA/09 infection, TNFα, IFNγ, and IL-2 responses against all peptide pools were higher in comparison to the unexposed cohort, and most of these increases were significant." (PMID 23526940, 2013). "In first stage of HTLV-I infection, most infected T cells require IL-2 to proliferate; however, later in infection, their proliferation is IL-2 independent." (PMID 24470860, 2013). "Several reports have also shown that a variety of proinflammatory cytokines can overcome Treg suppression during infection or in an inflamed environment, including IL-2, IL-4, IL-6, and TNF-α." (PMID 23593527, 2013). "PHA/IL-2 stimulated PBMCs were infected with 2 x 10-3 multiplicity of infection (MOI) of the CCR5-tropic subtype B strain Bal for three days and subsequently washed extensively to remove the inoculum." (PMID 23375046, 2013). "those that remain largely unmodulated by infection with either the avirulent or the virulent strain (IL-2, Il-12p35, TGF-β and IFN-β)." (PMID 22675469, 2012). "In this opinion article we discuss the dual roles of IL-2 as both a key inducer of Treg activity and also a target of Treg control during the acute phase of infection." (PMID 22807926, 2012). "In B10 mice, there was a shift in the predominant CD4 T cell-secreted cytokine from IFN-γ after infection to IL-2 after vaccination." (PMID 22457834, 2012). "Increased protection correlated with an increased percentage of TB10.4 specific IFNγ/TNFα/IL-2 or TNFα/IL-2 producing CD4 T cells at the site of infection." (PMID 22768165, 2012). "Very interestingly, H-1 PV is even able to enhance activated CD4+ T cell ability to release IL-2 right from the beginning of the infection, and IL-4 at early and late infection stages (24 h and 120 h after the inoculation)." (PMID 22359669, 2012). "A strong CD4+ proliferative T-cell response was observed at the early stage of infection, and IFN-γ, IL-2, and IL-5 were produced within the first weeks after infection whereas the detection of IL-10 was slightly delayed." (PMID 22400039, 2012). "CD4 T cells purified from the mediastinal lymph node (MedLN) and spleen on day 10 after NC infection of DR1 mice were tested for their ability to secrete IL-2, IFN-γ, or IL-4 after stimulation with defined peptide epitopes." (PMID 22457834, 2012). "In contrast, Nef activates NFAT and stimulates IL-2 release to overcome the exogenous requirement of IL-2 to promote T-cell proliferation, consequently disseminating the infection." (PMID 22719245, 2012). "The mean fold increase of US RNA (expression at day 4 compared to day 0) following infection of PHA/IL-2 activated, CCL19-treated and unactivated CD4+ T-cells was 21.1, 1.1 and 0.5 fold respectively (n = 5; p < 0.05 for all comparisons)." (PMID 21992606, 2011). "Taken together, these accumulated data indicate that dysregulation of the IL-2 pathway and/or the aberrant activation of the IL-2 autocrine loop are involved in the development of ATLL by the infection of CD4+ helper T cells with HTLV-I." (PMID 23675235, 2011).
infection (continued). "While, generation of effector cytokines, such as IFNγ and TNFα by the Th1 cells are known to be crucial for the resolution of M. tuberculosis infection, IL2 production by these T helper cells aids in the maintenance of memory immunity against infection." (PMID 21533158, 2011). "IFNγ and interleukin-2 (IL-2) responses following in vitro re-stimulation were measured by flow-cytometry prior to, during and more than one year post infection." (PMID 22144890, 2011). "Using this system we detected robust production of IL-2 to QE65 prior to gluten challenge or infection, and strong trends for production of IFN-γ and IL-17A produced in response to QE65." (PMID 21949691, 2011). "Prior to infection or challenge highly significant levels of IL-2 were produced upon stimulation with QE65 compared to medium alone." (PMID 21949691, 2011). "As expected, infection of IL-2/PHA activated cells with NL4.3Δenv led to reduced RT production and a 10 fold reduction in integrated HIV." (PMID 21992606, 2011). "Induction of IL-2 in peripheral blood started early at day 2 and was significantly elevated (p < 0.05) at day 4 post-infection compared with uninfected controls in CXCL-10-/- mice." (PMID 21439091, 2011). "IL-15 transcript levels returned to baseline values by day 5 pi, whereas IFN-γ and IL-2 induction was sustained until day 5 of infection." (PMID 21912714, 2011). "IL-2 protein levels were greater in healthy controls compared to patients with established infection." (PMID 21711552, 2011). "As at day 2 of infection, IL-2 levels were significantly higher than normal in mice immunized with ΔfupAΔcapB (5-fold) as well as in mice immunized with LVS (6-fold)." (PMID 20967278, 2010). "The enriched CD4+ T cells in the interface of density medium and plasma yielded approximately 98% purity; subsequently stimulated with phytohemagglutinin (0.5 ug/ml) and interleukin-2 (10-20 U/ml) before infection with virus stocks." (PMID 20064199, 2010). "Infection with IBDV resulted in transcriptional changes of mRNA encoding IFN-γ, IL-2 and IL-12p40 during the acute phase of the disease." (PMID 21143846, 2010). "By day 7 of infection, levels of IFNγ (90–250-fold), IL-6 (360–390-fold), IL-17 (30–75-fold), KC (20–35-fold), TNFα (5–13-fold), and IL-2 (2–3.5 fold) were significantly elevated above background in all three vaccinated groups." (PMID 20967278, 2010). "All other antigen specific IL-2 responses were significantly lower in both latent (p≤0.0007) and active infection (p≤0.02)." (PMID 21203487, 2010). "As observed with IL2-dependent T cells, sFc-CD134 blocked infection of MCC-CD134 efficiently with variants B19, B30, B31 and B32 while variants B14 and B28 proved more resistant." (PMID 20420700, 2010). "Although increased secretion of IL-2 was observed at the peak of oocysts shedding (day 14), the role of this cytokine in the termination of infection is unclear up to date." (PMID 19247447, 2009). "This IL-2 suppression is usually observed in early stages of infection with virulent parasite strains (proportional to stages of high parasite loads)." (PMID 19582140, 2009). "Subsequently, all eight animals were sacrificed and splenocyte cultures activated with Con A/IL-2 for five days prior to HIV-1R7/3 YU-2 Env GFP infection." (PMID 19144136, 2009). "One recent study showed that IL-2 signals to pathogen-specific CD8+ T cells during primary infection are crucial for the generation of robust secondary expansion of CD8+ memory T cells." (PMID 19901991, 2009). "Enhanced protection from infection was also demonstrated for IL-2 and IL-4 CYT-IVAC vaccinated mice further illustrating the adjuvant effect of membrane-bound IL-2 and IL-4." (PMID 19393093, 2009). "Studies performed in mice demonstrated that infection leads to increase of cycling cells, which are able to produce IL-2 and proliferate after in vitro activation." (PMID 19582140, 2009).
infection (continued). "Another T-cell cytokine, IL-2, plays a key role during infection by inducing proliferation/activation of CD4+ and CD8+ T cells, potentiates the cytotoxicity of CD8+ T lymphocytes and Natural Killer (NK) cells, and stimulates B lymphocyte function." (PMID 19440245, 2009). "In Se-adequate mice, the immune response appeared to be dominated by both Th1 and Th2 cytokines, as evident by increased expression of IFN-γ, IL-2, and IL-4 during the early stages of infection." (PMID 19247447, 2009). "The study of the cytokine profiles from the supernatant of proliferated MLN cells revealed that Se-adequate mice produced higher levels of Th1 (IFN-γ and IL-2) and moderate amounts of Th2 (IL-4) cytokines throughout the course of infection." (PMID 19247447, 2009). "On the other hand, NL-DT5R with SIVmac L6/7 (NL-DT5R6/7S) grew in CM primary cells in response to prolonged stimulation by PHA and IL-2 to reach titers, similar to those attained in cells with short stimulation, up to 8 days after infection." (PMID 19650891, 2009). "IL-2, IL-4, IL-5 levels on day 4 were significantly lower than the levels in moribund animals or in animals on day 11 post-infection (p < 0.001, Bonferroni corrected)." (PMID 19250545, 2009). "An enhanced expression of calcineurin able to activate the transcriptional factor NFAT to regulate IL-2 and TNFα production and the increase in local mast and goblet cells would point to an improved state of mucosal surveillance at sites of infection." (PMID 17825099, 2007). "Following infection and selection, stable and consistent production of biologically active IL-2 was demonstrated at both the mRNA and the protein level." (PMID 10070868, 1999). "Importantly, infection induced notable viral antigen expression and high levels of bioactive IL-2 secretion in interferon-competent systems, such as MDCK, A549, and HEK293T cells in vitro and in mice upon pulmonary delivery in vivo." (PMID 42012179, 2026). "Similarly to our previous data on PLWH, in the current study specific IFN-γ secretion was 4.3 times higher after MPXV infection than after vaccination and IL-2 secretion was 2.9 times higher." (PMID 41012178, 2025). "When we previously examined homotypic T‐cell responses following COVID‐19 in SOT recipients (E.g., ancestral responses following ancestral infection or BA.1 responses following BA.1 infection), we observed a hierarchy: IL‐2 monofunctional > polyfunctional > IFN‐γ monofunctional CD4+ subsets." (PMID 40605422, 2025). "In summary, while IFNγ and IL‐2 production from bulk T cells, as measured by Fluorospot, was maintained over time post‐infection in the complete cohort, a more detailed examination of S‐specific CD4+ T cells by ICS revealed subset and polyfunctional (3–4 cytokine) responses that declined over time." (PMID 41427434, 2025). "Post-operatively, IL-2 concentration and IL-2R expression decrease, with a nadir around days 3–4 post-operatively, which corresponds with the timing of the development of post-operative infections in our cohort." (PMID 41148718, 2025). "A possible contributing factor to this observation may be the dynamic change of IL-2 levels in Mtb infection, where IL-2 levels have been shown to decrease with the extension of infection time." (PMID 40861457, 2025). "Finally, interleukin-2 (IL-2) signaling is known to drive the formation of Th1 precursor cells and also sustain Th1 responses during later stages of infection." (PMID 41036542, 2025). "HBoV1 infection increases the concentrations of IL-2, IL-4, IL-10, and IL-13 in patients." (PMID 39846742, 2025). "IL2 is a characteristic cytokine of the Th1 immune response, stimulates the growth of T helper, cytotoxic and regulatory T cells, and also promotes the differentiation of T cells into effector T cells and memory T cells, which helps the body fight infection." (PMID 41157660, 2025).
infection (continued). "Together, Jurkat–SMPU reporter cell clones 21 and 29 stimulated with PHA-P and IL-2 were identified as a suitable cell culture system to be used in infection experiments due to their Tax-responsiveness, high efficiency in activating GFP expression, and limited background activity." (PMID 39599568, 2024). "In brief, CAR T cell manufacturing included depletion of CD14+ and CD25+ cells, CD3/28 bead stimulation, transduction with lentivirus at multiplicity of infection of 0.3, removal of beads at day 7–9, followed by expansion for a total of 12–17 days in interleukin (IL)-2 and IL-15 cytokines." (PMID 38867077, 2024). "In addition, the lagging release of IFN-γ and IL-2 in 610A2T-infection indicated that Th1 type was disinhibition in the later stage and also involved in the host’s defence against the pathogen." (PMID 38903940, 2024). "After mpox infection, IL-2 ELISpot results positively correlated with CD8+ T cells (p < 0.05)." (PMID 38400115, 2024). "This becomes rate‐limiting during the course of an infection and efficient competition for IL‐2 requires the persistent expression of CD25 which can be enhanced by other cytokines such as type‐I IFNs and IL‐12 or suppressed by cytokines such as IFNγ and promotes additional rounds of cell division." (PMID 38039407, 2024). "The presence of a primary transcript attributable to IL-2 in macrophages in both infections." (PMID 38399810, 2024). "IL-2/S4B6 injection from day 1 to day 3 post-infection potentiated IL-2Rα expression, ERK and AKT activation, and S6 phosphorylation in both OT-I WT and OT-I Mrtfab−/− cells at day 4, and restored activation and proliferation of OT-I Mrtfab−/− cells to levels comparable to wildtype." (PMID 39261466, 2024). "Finally, 50 and 100 mg/kg baicalin increased IL-2 and IL-8 mRNA expression compared to that in the infection group (P < 0.001)." (PMID 39075562, 2024). "Similarly, high IL-2 and IL-4 levels have been reported in children with severe CAP, indicating that severe infection, like that seen in our study, is associated with elevated cytokine levels." (PMID 39737297, 2024). "Taken together, these results suggested that intranasal boosting with the RBD-HR vaccine induced a Th1-biased cellular immune response characterized by TNF-α and IL-2 secretion, which has significant implications in the prevention of infection and limiting the spread of SARS-CoV-2." (PMID 38550714, 2024). "Moreover, such an inflammatory reaction, with increased proliferation of the effector cells due to the production of IL-2, will provide more effective protection after immunization with ai-Nbs in response to infection with C. muridarum." (PMID 38396724, 2024). "In line with allogeneic HCT recipients, our data also showed that both IL-2- and IFN-γ + IL-2-producing cellular responses against SARS-CoV-2 vaccination or infection were associated with the memory phenotype of T- and B-lymphocytes among healthy subjects without hematological disease." (PMID 38842630, 2024). "IL-2 is important in immune cell survival, expansion, and immunity against infection." (PMID 38164134, 2023). "DHAV infection could lead to the different expression of various cytokines in young ducklings; for example, the transcription of IL-1β, IL-2, IL-4, IL-6, IL-8, and IL-10 was highly stimulated after infection." (PMID 37391858, 2023). "IL-2 production by undifferentiated T cells with antigens suggests a very early stage of infection." (PMID 37520555, 2023). "In addition, lycopene can improve broiler fertility by enhancing sperm performance and reducing inflammation by modulating the levels of interleukin 1, 2, and 10 (IL-1, IL-2, and IL-10) in cases of infection." (PMID 37426426, 2023).
infection (continued). "The first study used a dose of 0.5 million IU/day for SLE patients with infection (5-day course), revealing that low-dose IL-2 treatment upregulated the number of total T cells, B cells, CD4+ T cells, CD8+ T cells, Th1, Th17, and Treg cells, which were similar to those in healthy controls." (PMID 38164134, 2023). "We have determined that ablation of both the B and T lymphocyte compartments and additional cytokine signaling via the IL-2/7 common gamma chain receptor in mice allows permissiveness to D. immitis tissue-phase larval development for at least the first 28 days of infection." (PMID 37426014, 2023). "We can only speculate, based on reports on murine CD8+ and CD4+ T cells in experimental infection, that augmented IL-2 production in tissue-derived T cells might contribute to more robust memory formation." (PMID 37815874, 2023). "Rotavirus-infected rats exhibited higher levels of interleukin-2 (IL-2), and interleukin-10 (IL-10), and the increased levels were partially reversed when aspirin was administered in conjunction with infection." (PMID 37848986, 2023). "In addition, H3N2-specific CD8β+ T cell IL-2 responses were also induced in this group, reaching 0.13% 14 dpi and then gradually declining over the course of infection." (PMID 37287962, 2023). "Taken together, these results indicate that Malat1scr/scr cells in the context of a viral or bacterial infection receive relatively poor activating cues and subsequently produce less IL-2 early during infection, contributing to a less robust pro-survival and pro-memory state." (PMID 38127070, 2023). "Interestingly, duRIG-I-CARD- or full-length duRIG-I- (DTMUV infection) mediated pro-inflammatory cytokines (IL-1β, IL-2, IL-6, IL-8) expression level was significantly promoted by overexpression of duLGP2." (PMID 35784309, 2022). "In some experiments, T cells were also activated by Phorbol myristate acetate (PMA) for 2 h for Jurkat cells or by a combination of IL2 + CD3 + CD28 for 3 days for primary T cells before infection, considering a large proportion of T cells is activated in human." (PMID 35277473, 2022). "In addition, VV-IL-37-GFP infection significantly increased the levels of IL2, IFN, and TNF in HCC mice." (PMID 36146619, 2022). "Virus-specific and virus-neutralizing antibody titers rapidly declined in convalescents over 9 months after infection, whereas virus-specific cytokine-producing polyfunctional T cells persisted, among which IL-2-producing T cells correlated with virus-neutralizing antibody titers." (PMID 35013191, 2022). "Interestingly, we also found that the number of ESAT6/CFP10-specific IFN-γ/IL-2 cells was greater in the infection group than in the BC02 adjuvant group, or the AEC/BC02 vaccine group." (PMID 35632581, 2022). "Previous studies have reported that the amount of IL-2 produced by T cells from patients and mice with SLE is reduced, which is thought to contribute to increased susceptibility to infection, reduced activation-induced cell death, and subsequent prolonged survival of autoreactive lymphocytes." (PMID 36203602, 2022). "In our study, adaptive cytokine responses, as indicated by IFNγ, IL-2 and the IFNγ−inducible chemokine IP-10, were elevated in individuals with any prior exposure to C. burnetii, whether through vaccination or infection." (PMID 35812430, 2022). "After infection of germ-line NR2F6-deficient mice with Listeria, CD8 CTLs enhanced antigen-specific immune memory cell formation and inflammatory cytokine secretion, such as IFN-γ, TNF-α, and IL-2." (PMID 36389159, 2022). "The cross-reactive IL-2 secreting T cells associated with absence of infection did not co-produce IFN-γ, suggestive of a pre-existing antigen-specific memory T cell population." (PMID 35013199, 2022). "induced significant IL-2 production the lungs or spleen during primary or secondary infection." (PMID 36032120, 2022).